MDM2 (MDM2 proto-oncogene)
Diseases named in the same sentence as MDM2 in open-access papers (continued):
Sharing a sentence is not in itself a finding about the gene and the disease.
cancer (continued). "In addition, we have also shown that the chaperone network, which assists cancer cells to survive in the presence of chemotherapeutics, was completely remodeled after transformation with MDM2 oncoprotein." (PMID 29137250, 2017). "Our previous study indicated that splicing factor hnRNPA1 could bind to the human homologue of mouse double minute (MDM2), an oncogene which has been observed to be over-expressed in numerous types of cancers." (PMID 28035066, 2017). "In this research, we investigated whether and how estradiol correlate to cancer cell behaviors through heterogeneous nuclear ribonucleoprotein (hnRNPA1) and MDM2." (PMID 28035066, 2017). "MDM2 overexpression is found in many different types of cancers." (PMID 28615518, 2017). "Blocking interactions with MDM2 is a prime strategy for new cancer drug development." (PMID 28835687, 2017). "Therefore, it is imperative to understand and further investigate these various MDM2 isoforms and the role they play in cancer." (PMID 29065514, 2017). "In AAN, the expression of MDM2 is down-regulated, but has-miR-192 is over-expressed in renal cells after AA treatment, indicating that MDM2 is related to cell cycle and AAN-associated cancers." (PMID 27418141, 2016). "These suggested that publication bias might not have severe influence on the results of the current meta-analysis on the association between MDM2 SNP285 polymorphism and cancer risk." (PMID 27890964, 2016). "Therefore, we performed this meta-analysis to obtain a more precise estimation between MDM2 SNP285 polymorphism and risk of cancer." (PMID 27890964, 2016). "PP2A inhibition-induced sensitization to radiation and chemotherapy in cancer cells is believed to occur via several mechanisms, including sustained phosphorylation of Akt, MDM2, Plk1, TCTP and Cdk1, which are involved in apoptosis, cell cycle deregulation, and inhibition of DNA repair." (PMID 27527863, 2016).
cancer (continued). "Hence, we performed a meta-analysis to provide a more precise estimation of the relationship between MDM2 SNP285 polymorphism and cancer risk." (PMID 27890964, 2016). "MDM2 upregulation has been found in various types of cancer, including MM." (PMID 27916892, 2016). "As MDM2 antagonists are being developed as an alternative treatment to chemotherapy for cancer treatment, it is of note that MDM2 inhibition might be detrimental for normal tissues, especially for kidney as our data suggest." (PMID 27882940, 2016). "Since MDM2 inhibitors such as nutlin-3 or RG 7112 are now being under extensive investigation for the treatment of cancer by recent research works, application of those drugs for the treatment of VC may be anticipated." (PMID 26832969, 2016). "MDM2 has been considered as a target for human cancer therapy." (PMID 27004407, 2016). "By understanding the molecular mechanisms regulating MDM2 splicing in response to damage and potentially in cancer we have paved the way for the development of novel splice modulation strategies for adjusting MDM2 levels in cancers with elevated MDM2-ALT1 and SRSF1 expression." (PMID 25845590, 2015). "The MDM2 gene is an oncogene that is amplified in many human cancers." (PMID 25888903, 2015). "In conclusion, JapA represents a new class of MDM2 inhibitor that exerts its anticancer activity through directly down-regulating MDM2, and might be developed as a novel cancer therapeutic agent." (PMID 25739118, 2015). "Overexpression of MDM2 due to genomic amplification occurs in a variety of solid human cancers." (PMID 25888903, 2015).
cancer (continued). "Since Set7/9KD cells exhibit elevated levels of Mdm2 expression, we questioned whether the product of this gene may negatively affect DNA repair and thus affect the survival of cancer patients." (PMID 26317544, 2015). "The interaction between Mdm2 and TFII-I might therefore have negative implications for CMV promoter-based gene therapy in cancers over-expressing Mdm2." (PMID 26656605, 2015). "Ultimately, the insights provided in this work have distinct diagnostic implications and suggest the possibility that targeting MDM2 or ATRX by small molecule in a combination with CDK4 inhibitor might be promising for cancer therapy." (PMID 26697514, 2015). "Therefore, we designed this study to identify compounds that have direct inhibitory effects on MDM2 for the treatment of cancer." (PMID 25739118, 2015). "Next, we thought to determine whether a correlation between the expression profiles of Set7/0 and Mdm2 may affect the survival of cancer patients." (PMID 26317544, 2015). "There is an increasing interest in developing MDM2 inhibitors for cancer therapy." (PMID 25739118, 2015). "Furthermore, JapA directly bound to MDM2 protein and reduced MDM2 levels in cancer cells in vitro and in vivo by promoting MDM2 protein degradation and inhibiting MDM2 transcription, which is distinct from the existing MDM2 inhibitors." (PMID 25739118, 2015). "Our observation that Mdm2 over-expression can decrease the ability of TFII-I to activate the CMV promoter might have implications for the efficiency of experimental gene therapy based on CMV promoter–derived vectors in cancers with Mdm2 gene amplification." (PMID 26656605, 2015). "We and others have demonstrated that MDM2 is a promising molecular target for cancer therapy." (PMID 25739118, 2015).
cancer (continued). "A well-studied SNP in MDM2, SNP309, has also been linked to increased cancer risk." (PMID 26416416, 2015). "Overexpression of MDM2 due to genomic amplification occurs in a variety of human cancers." (PMID 24968304, 2014). "The current study was initiated to address these questions, and to test the possibility that tetraploid cancer cells may be especially sensitive to MDM2 antagonists." (PMID 25380055, 2014). "The effect of chiMDM2s on the growth of cancer cells with high MDM2 expression was examined." (PMID 25621298, 2014). "MDM2 overexpression is detected in a number of human cancers [-]." (PMID 25326024, 2014). "Overexpression of MDM2 has been demonstrated in many human cancers." (PMID 25949795, 2014). "Many of the 12q fusion genes produced chimeric proteins or disrupted cancer-associated genes such as RUNX2, CCND3, and LRP1, indicating that some of the fusions may contribute to cancer progression independently of MDM2/CDK4 co-amplification." (PMID 25300797, 2014). "In humans, MDM2 is amplified and / or overexpressed in many cancer types." (PMID 25327560, 2014). "Taken together, these results suggest that TSPO/MDM2 dual-target ligands could represent a new attractive multi-modal opportunity for anti-cancer strategy in GBM." (PMID 24756113, 2014). "Further research examining the signaling events and factors that regulate normal splicing of MDM2 and also the misregulated splicing observed in cancers will be critical for identifying therapeutic strategies for treatment of tumors harboring aberrantly spliced isoforms of MDM2 and MDMX." (PMID 25105592, 2014). "Also, INZ sensitizes the anti-cancer effect of cisplatin, doxorubicin, or Nutlin-3 (an MDM2 inhibitor) as tested in xenograft cancer models." (PMID 25347121, 2014).
cancer (continued). "This suggests that MDM2-C may be used as a prognostic biomarker for cancers that have gained an MDM2 oncogenic pathway." (PMID 24147044, 2013). "As both RNPC1 and Mdm2 expression is altered in several types of human cancers, this regulation may represent an important mechanism for cancer development and RNPC1 may be used for targeting tumors with high Mdm2 expression." (PMID 23912475, 2013). "In addition, we show that rapamycin effectively inhibits MDM2 expression and sensitizes cancer cells to chemotherapy." (PMID 23638184, 2013). "In addition, we show that rapamycin effectively inhibits MDM2 expression and sensitizes cancer cells to chemotherapeutic drug-induced apoptosis." (PMID 23638184, 2013). "Since altered expression of RBPs has been found in many types of human cancer, understanding how Mdm2 is regulated by RBPs and whether this regulation contributes to tumorigenesis might provide novel therapeutic strategies for cancer treatment." (PMID 23912475, 2013). "Since the potential ligand-binding pocket in GIG47 is hydrophobic in nature like that in mdm2, above strategy may also prove to be useful in developing anti-cancer agents using inhibitors against GIG47." (PMID 22748190, 2012). "Probing biological functions and mechanisms of MDM2 regulation would require further integration of computational and experimental studies and may help to guide drug design of novel anti-cancer therapeutics." (PMID 22815859, 2012). "Consequently, to identify MDM2/MDMX dual-inhibitors opens a new era of anti-cancer drug development." (PMID 22949826, 2012). "MDM2 plays an essential role in cancer development and progression." (PMID 22911819, 2012). "We therefore aimed to develop peptides representing the MDM2-CK1α interface in order to uncover potentially novel concepts in cell growth control and to develop novel therapeutic leads for targeting this complex in cancer cells." (PMID 22916255, 2012).